CLIC4 (CLIC family member 4)
Diseases named in the same sentence as CLIC4 in open-access papers (continued):
Sharing a sentence is not in itself a finding about the gene and the disease.
tumor (37 papers, 2005 to 2025). "An enrichment analysis also indicated that CLIC4 is associated with the tumor microenvironment, particularly the extracellular matrix (ECM)." (PMID 39595145, 2024). "Chloride intracellular channel 4 (CLIC4), a tumor suppressor, was downregulated in tumor cells when compared to tumor-associated fibroblasts and endothelial cells, supporting its role in growth arrest, differentiation, and apoptosis." (PMID 39409886, 2024). "Transcriptional profiles of both primary tumors and pre-metastatic lungs of tumor-bearing CLIC4-deficient hosts were consistent with a microenvironment where inflammatory pathways were elevated." (PMID 35727842, 2022). "Our proteomic and transcriptomic analyses yielded an unrecognized consequence of host CLIC4 loss for enhancing the inflammatory milieu of the primary tumor site." (PMID 35727842, 2022). "We found evidence that CLIC4-deficient tumor-bearing mice differed from WT mice in the pattern of circulating factors, some of which are associated with migration and adhesion of leukocytes." (PMID 35727842, 2022). "The loss of CLIC4 has also been demonstrated in the tumor environments of squamous tumors of the esophagus." (PMID 32116799, 2020). "While CLIC1 has generally been associated with tumor progression in prior studies, there are some contradictions regarding the role of CLIC4 in tumors." (PMID 30282979, 2018). "During carcinogenesis, CLIC4 mirrors the dual nature of TGF-β in causing context dependent tumor suppression or enhancement." (PMID 27536941, 2016). "By building membrane protein platforms with tumor microenvironment receptors, such as β-integrin, CLIC4 was observed to profoundly affect the conduction of tumor metastasis-associated pathways, thereby altering the tumor microenvironment to promote tumor invasion and metastasis." (PMID 37199665, 2023). "Despite implantation of identical 6DT1 cells, CLIC4 deficiency in the host microenvironment led to relative increases in many factors within the primary tumor proteome, including pro-inflammatory cytokines such as CCL3, also known as macrophage inflammatory protein 1-alpha, at both 14 and 28 days." (PMID 35727842, 2022). "Additionally, anti-inflammatory IL-4 was significantly lower in the tumors of Clic4 KO hosts at 28 days, suggesting net increases in the inflammatory milieu upon CLIC4 loss in the tumor microenvironment." (PMID 35727842, 2022). "These functions may have contributed to necrosis in the primary tumor and reduced expression of genes involved in angiogenesis in the premetastatic lungs of CLIC4-deficient mice." (PMID 35727842, 2022). "Given the association with TGF-β pathway, CLIC4 could be directly involved in ROS mediated mechanisms for tumor growth." (PMID 32116799, 2020). "This early discovery provided a foundation for understanding CLIC4’s regulatory effects within the tumor microenvironment." (PMID 39595145, 2024). "The expression of CLIC4 is significantly correlated with tumor grade, tumor invasion, and poorer overall survival." (PMID 39027429, 2024). "CLIC4 expression levels were negatively correlated with pDCs and Treg cells, both of which primarily exhibit pro-tumor effects." (PMID 39595145, 2024). "The analysis of CLIC4 immunoexpression in the tumor stroma showed high expression of this protein in OSCC when compared to OVC." (PMID 37026609, 2023). "CLIC4 immunoexpression in the OSCC parenchyma was observed in all the extension of the tumor, except in the areas where keratin pearls were formed." (PMID 37026609, 2023). "Concerning the CLIC4 role in the tumor stroma, we observed a significantly higher immunoexpression in the OSCC stroma." (PMID 37026609, 2023). "GFP-positive tumor cells were detected in the lungs of both WT and Clic4 KO mice 2 days after tail vein injection." (PMID 35727842, 2022). "What’s more, it has been reported that CLIC4 overexpression can inhibit the epithelial-mesenchymal transition in tumor cells." (PMID 35397614, 2022).
tumor (continued). "Previous reports showed that CLIC4-deficient mice had lower circulating levels of CCL5 than controls after LPS treatment, a finding we now extend to plasma of tumor-bearing mice." (PMID 35727842, 2022). "In fact, elevated reactive oxygen species was identified in the GSEA analysis of both the primary tumor and the premetastatic lungs of CLIC4 KO mice." (PMID 35727842, 2022). "Based on the DESeq2 analysis of the primary tumor data, we applied GSEAPreranked to interrogate Hallmark pathways, which yielded normalized enrichment scores (NES) plotted as Clic4 KO mice relative to WT mice." (PMID 35727842, 2022). "These proteins were initially identified as blood biomarkers of OC because human CLIC1 and CLIC4 were found into the blood of xenografted tumor-bearing mice and were significantly elevated in sera of EOC patients." (PMID 33562306, 2021). "Those that were known as oncogenic or tumor suppressive were positively or negatively correlated with CLIC4, respectively (such as miR-181 family and miR-10a)." (PMID 33014825, 2020). "Extensive studies by Yuspa’s group have revealed CLIC4 to have a dual role in tumor environment where its expression is lost early in tumor cells while it is increased in stromal cells." (PMID 32116799, 2020). "Replacing the tumor expression of CLIC4 is shown to repress tumor growth as shown by in vitro studies in tumor cell culture as well as orthografts in in vivo models." (PMID 32116799, 2020). "The status of CLIC4 in tumor vs. normal scenarios in terms of a membrane protein acting as a channel or cytoplasmic protein performing other functions for the cell is yet to be elucidated." (PMID 32116799, 2020). "CLIC4 expression is positively correlated with tumor grade, lymph node metastasis, tumor invasion and poor overall survival in ductal adenocarcinoma of the pancreas." (PMID 32116799, 2020). "CLIC1 and CLIC4 were initially identified as blood biomarkers of EOC because human CLIC1 and CLIC4 were shed into the blood of xenografted tumor-bearing mice and significantly elevated in sera of EOC patients." (PMID 30282979, 2018). "In this study, a key finding is that at the tissue level either CLIC1 or CLIC4 stained larger percentages of the EOC tumor cores, across all major EOC subtypes, compared to CA125." (PMID 30282979, 2018). "Our data suggest that inhibiting CLIC4 in EOC cell lines decreases cell proliferation and metastasis, and that elevated tumor CLIC4 correlates with reduced patient survival." (PMID 30282979, 2018). "We observed a similar gradual reduction of nuclear CLIC4 staining and increased cytoplasmic staining with increased malignancy, suggesting tumor progression-related changes in intracellular CLIC4 localization." (PMID 30282979, 2018). "In the tumor stroma, on the other hand, CLIC4 is often upregulated and it plays a critical role in myofibroblast transition." (PMID 30201851, 2018). "In this study, we evaluated CLIC1 and CLIC4 staining of EOC in tissue microarrays as well as fresh tumor tissue secretomes to complement our prior human serum biomarker studies." (PMID 30282979, 2018). "In summary, anti-inflammatory CLCN3 signaling and high levels of Parabacteroides merdae combined with anti-oncogenic TGF-β/CLIC4 signaling exhibited an anti-tumor effect." (PMID 28445967, 2017). "Elevating CLIC4 levels in tumor epithelium suppresses tumor growth that is coincident with enhanced TGF-β signaling." (PMID 27536941, 2016). "This implies that reactivating or restoring CLIC4 expression in tumor cells, or reducing its expression in the tumor stroma, may offer novel strategies for inhibiting tumor growth." (PMID 39595145, 2024). "Although the precise mechanism by which CLIC4 functions as a tumor suppressor or matrix activator remains unclear, increasing evidence suggests its clinical relevance." (PMID 39595145, 2024). "These combined findings indicate that CLIC4 may be a key player in stromal remodeling contributing to a supportive tumor microenvironment." (PMID 39595145, 2024).
tumor (continued). "Since CLIC4 expression levels vary across different tumors, either increasing or decreasing, the precise mechanism by which CLIC4 acts as a tumor suppressor or promoter remains unclear." (PMID 39595145, 2024). "Recent studies have shown that the CLIC4 gene is closely related to tumor progression." (PMID 39595145, 2024). "CLIC4 protein plays a role in the cell cycle and apoptosis regulation and participates in the myofibroblasts transdifferentiation process, which are the main cells of the tumor stroma." (PMID 37026609, 2023). "The loss of these CLIC4 functions could contribute to the altered immune milieu of primary tumor and lung in Clic4 KO hosts detected by transcriptomic analysis." (PMID 35727842, 2022). "For example, our CIBERSORT analysis identified enrichment for macrophage M1 polarization in primary tumors in the KO host, suggesting qualitative but not quantitative differences of tumor-infiltrating macrophages in CLIC4-deficient animals." (PMID 35727842, 2022). "Alternatively, messages from the primary tumor growing in Clic4 KO mice may be ineffective for conditioning the distant metastatic bed." (PMID 35727842, 2022). "Host CLIC4 could be required at multiple steps of the metastatic process either at the primary tumor or distant sites leading to lung metastases." (PMID 35727842, 2022). "We also directly compared the premetastatic lungs of tumor bearing mice of each genotype and identified relative reductions in two established CLIC4-regulated pathways, angiogenesis and TGF-β signaling, among the pathways that distinguished Clic4 KO from WT lungs." (PMID 35727842, 2022). "Furthermore, in vitro experiments demonstrated that CLIC1 and CLIC4 knockdown slowed the proliferation and migration of OC cells, indicating a potential role in tumor progression." (PMID 33562306, 2021). "It would be interesting to investigate how endoplasmic reticulum/mitochondrial localization of CLIC4 could possibly be affecting tumor metabolism." (PMID 32116799, 2020). "CLIC4 is the other well studied CLIC member in tumor biology, along with CLIC1." (PMID 32116799, 2020). "The discrepancy about whether CLIC4 induces or inhibits tumor growth might be dependent upon the subcellular localization of CLIC4 in tumor cells, at least for some tumor types." (PMID 30282979, 2018). "Thus, it is possible that the role of CLIC4 in tumors depends both upon its distribution between stromal and tumor cells and its subcellular location, especially in the tumor cells." (PMID 30282979, 2018). "Other studies have indicated that CLIC1 and CLIC4 may play roles in altering the EOC tumor microenvironment and affecting EOC tumor progression." (PMID 30282979, 2018). "Likewise, in EOC, CLIC4 exhibits strong stroma and tumor cell staining and plays a possible role in TGFβ-mediated fibroblast activation." (PMID 30282979, 2018). "Taken together these results suggest that CLIC4 could serve as a marker for EOC tumor staging and possibly prognosis." (PMID 30282979, 2018). "CLIC4 was first characterized as intracellular chloride channel, later shown to be involved in signaling, cytoskeleton integrity and differentiation and is a tumour suppressor gene in cutaneous squamous cell cancer." (PMID 27124473, 2016). "More precisely, FLNA FBLN1, MYL9, CLIC4 all have demonstrated tumour suppressor activity." (PMID 27124473, 2016). "However, it is noteworthy in numerous studies that CLIC4 may influence tumor growth and development through the tumor stroma." (PMID 39595145, 2024). "Thus, crosstalk between the tumor and host stroma involves changes in CLIC4 expression." (PMID 35727842, 2022). "Finally, the effects of CLIC1 and CLIC4 on tumor growth and migration suggest that they may be therapeutic targets and should be further investigated." (PMID 30282979, 2018). "Furthermore, CLIC4 has been proven to suppress tumor cell growth by enhancing TGF-β responsiveness." (PMID 28445967, 2017).
tumor (continued). "Thus, CLIC4 has been suggested to have a suppressive effect on tumor development." (PMID 24503901, 2014). "We focused on CLIC4, a member of the chloride intracellular channel protein family, because previous studies suggested that some chloride channels and chloride channel regulators could function as tumor suppressors." (PMID 24503901, 2014). "We here focused on CLIC4 to investigate its potential involvement in carcinogenesis in the lung because previous studies suggested that some chloride channels and chloride channel regulators could function as tumor suppressors." (PMID 24503901, 2014). "We here focused on CLIC4, a chloride intracellular channel protein, because previous studies suggested that some chloride channels and chloride channel regulators could function as tumor suppressors." (PMID 24503901, 2014). "Mechanistically, the loss of FTO increases the m6A levels of chloride intracellular channel 4(CLIC4) and ERG2, which are two tumor suppressors in PCa, accelerating their degradation." (PMID 39268470, 2024). "It is important to emphasize that CLIC4 and α-SMA are upregulated proteins co-located in the myofibroblasts present in the tumor stroma, which can demonstrate CLIC4 participation in the differentiation process of these cells." (PMID 37026609, 2023). "Although large GFP-positive metastases were detected in wildtype mice 14 days after tail vein injection, only a few small GFP-positive metastases developed in the Clic4 KO lungs although individual GFP-positive injected tumor cells persisted in both genotypes." (PMID 35727842, 2022). "Studies implied that CLIC4 also induced the NF-κB-dependent activation of HIF (hypoxia-inducible factor) and participated in tumor growth through its microenvironmental function." (PMID 33014825, 2020). "Recent studies has shown that CLIC4, an integral component of TGF-β signaling, has been proven to either enhance or inhibit tumor growth depending on the tumor type." (PMID 33014825, 2020). "Consistent with broad staining across nearly all EOC tumor cores, CLIC1 and CLIC4 were also shed more consistently and at higher levels from fresh human tumors across tumor subtypes than CA125." (PMID 30282979, 2018). "In contrast, elevating CLIC4 in tumor stroma via TGF-β and p38 signaling enhances tumor growth and tumor cell invasion." (PMID 27536941, 2016). "Among these were several genes with known tumour suppressor activity (e.g. FLNA, FBLN1, MYL9, CLIC4 and SEC23A)." (PMID 27124473, 2016). "For example, three chloride intracellular channel genes (CLIC3, CLIC4, and CLIC5) were down-regulated, while CLIC6 was up-regulated three-fold in tumor tissues." (PMID 24466154, 2014). "Our results showed that CLIC4 may participate in the CAF differentiation, which may reflect the differences in biological behavior between these neoplasms." (PMID 37026609, 2023). "The absence of host CLIC4 did not affect primary tumor weight, but nearly eliminated the number of lung metastases at 28 days post-implantation of 6DT1 tumor cells." (PMID 35727842, 2022). "Nevertheless, the deletion of CLIC4 did not interfere with the ability of tumor cells to form a primary tumor and spread metastatically in WT hosts." (PMID 35727842, 2022). "Of note, however, primary tumor weight was not affected, nor was primary tumor cell density diminished by growth in Clic4 KO hosts." (PMID 35727842, 2022). "The near total inhibition of metastasis by Clic4 depletion in the host suggests that fundamental host requirements for metastatic competence, irrespective of tumor heterogeneity and high EMT, have been modified." (PMID 35727842, 2022).
tumor (continued). "Immunohistochemical analysis showed both primary tumor and metastases from sgClic4 tumor-bearing mice lacked CLIC4 in tumor cells while host stromal cells were positive." (PMID 35727842, 2022). "In the absence of host CLIC4, the microenvironment of the primary tumor and the pre-metastatic lungs is unfavorable for tumor viability and lung colonization." (PMID 35727842, 2022). "Similar to CLIC4, CLIC5 was also reported in mitochondria where it plays a role in modulation of ROS, which could also contribute to tumor signaling." (PMID 32116799, 2020). "In this study we evaluated the utility of CLIC1 and CLIC4 as EOC tissue biomarkers because we previously showed they are promising EOC serum biomarkers and have intriguing, but incompletely understood roles in EOC tumor progression." (PMID 30282979, 2018). "Elevated CLIC4 expression, but not CLIC1 expression, was a negative indicator of patient survival, and CLIC4 knockdown in cultured cells decreased cell proliferation and migration indicating a potential role in tumor progression." (PMID 30282979, 2018). "CLIC1 and CLIC4 staining were not significantly affected by clinicopathological parameters such as age, race, disease stage, tumor grade, or tumor size." (PMID 30282979, 2018). "CLIC1 staining of the malignant EOC tumors was observed only within the tumor nests but not in the adjacent stroma, whereas CLIC4 stained both tumor nests and surrounding stroma." (PMID 30282979, 2018). "While secretion of CLIC4 in vivo has not been documented, its release in extracellular vesicles could influence local and distant sites of tumor growth." (PMID 35727842, 2022). "Similarly, in cutaneous squamous cell cancer, nuclear localization of CLIC4 was associated with increased TGF-β-dependent transcriptional activity and tumor growth inhibition whereas the absence of nuclear CLIC4 enhanced tumor development." (PMID 30282979, 2018). "That is restriction of CLIC4 to the cytoplasm and not the nucleus of the tumor cells may increase cell proliferation and tumor progression." (PMID 30282979, 2018).
bacterial infection (1 paper, 2014). "CLIC4 is also shown to play a role in immune response of macrophages to LPS and in the host defense against bacterial infection." (PMID 24809979, 2014).
epithelial neoplasm (1 paper, 2023). A benign or malignant neoplasm that arises from and is composed of epithelial cells. "In our study, CLIC4 immunoexpression was evaluated in two epithelial neoplasms with different biological behavior." (PMID 37026609, 2023).
kidney diseases (1 paper, 2014). "Considering these findings, further analysis of CLIC4 function in the kidney and possible dysfunction in human kidney diseases needs to be addressed." (PMID 24886590, 2014).
neurodegenerative disease (1 paper, 2018). A disorder of the central nervous system characterized by gradual and progressive loss of neural tissue and neurologic function. "Targeting CLIC4 in neurons may therefore provide a therapeutic approach for managing progressive neurodegenerative diseases that arise from neuronal apoptosis." (PMID 30237421, 2018).
CLIC4 also shares sentences with these, for which no sentence is quoted: colorectal (3 papers); hepatocellular carcinoma (3); infection (3); liver cancer (3); benign tumors (2); dry age related macular degeneration (2); acute myocarditis (1); age-related macular degeneration (1); allergic asthma (1); Alzheimer disease (1); atherosclerosis (1); autoimmune disease (1); benign ovarian tumors (1); cardiomyopathy (1); colorectal cancer (1); endothelial dysfunction (1); head and neck cancer (1); kidney (1); leukemia (1); lung adenocarcinoma (1); lymphoma (1); metastatic disease (1); necrotizing enterocolitis (1); Salmonella Infections (1); Stroke (1).